PRKCE (protein kinase C epsilon)
Description:
Calcium-independent, phospholipid- and diacylglycerol (DAG)- dependent serine/threonine-protein kinase that plays essential roles in the regulation of multiple cellular processes linked to cytoskeletal proteins, such as cell adhesion, motility, migration and cell cycle, functions in neuron growth and ion channel regulation, and is involved in immune response, cancer cell invasion and regulation of apoptosis. Mediates cell adhesion to the extracellular matrix via integrin-dependent signaling, by mediating angiotensin-2-induced activation of integrin beta-1 (ITGB1) in cardiac fibroblasts. Phosphorylates MARCKS, which phosphorylates and activates PTK2/FAK, leading to the spread of cardiomyocytes. Involved in the control of the directional transport of ITGB1 in mesenchymal cells by phosphorylating vimentin (VIM), an intermediate filament (IF) protein. In epithelial cells, associates with and phosphorylates keratin-8 (KRT8), which induces targeting of desmoplakin at desmosomes and regulates cell-cell contact. Phosphorylates IQGAP1, which binds to CDC42, mediating epithelial cell-cell detachment prior to migration. In HeLa cells, contributes to hepatocyte growth factor (HGF)-induced cell migration, and in human corneal epithelial cells, plays a critical role in wound healing after activation by HGF. During cytokinesis, forms a complex with YWHAB, which is crucial for daughter cell separation, and facilitates abscission by a mechanism which may implicate the regulation of RHOA. In cardiac myocytes, regulates myofilament function and excitation coupling at the Z-lines, where it is indirectly associated with F-actin via interaction with COPB1. During endothelin-induced cardiomyocyte hypertrophy, mediates activation of PTK2/FAK, which is critical for cardiomyocyte survival and regulation of sarcomere length. Plays a role in the pathogenesis of dilated cardiomyopathy via persistent phosphorylation of troponin I (TNNI3). Involved in nerve growth factor (NFG)-induced neurite outgrowth and neuron morphological change independently of its kinase activity, by inhibition of RHOA pathway, activation of CDC42 and cytoskeletal rearrangement. May be involved in presynaptic facilitation by mediating phorbol ester-induced synaptic potentiation. Phosphorylates gamma-aminobutyric acid receptor subunit gamma-2 (GABRG2), which reduces the response of GABA receptors to ethanol and benzodiazepines and may mediate acute tolerance to the intoxicating effects of ethanol. Upon PMA treatment, phosphorylates the capsaicin- and heat-activated cation channel TRPV1, which is required for bradykinin-induced sensitization of the heat response in nociceptive neurons. Is able to form a complex with PDLIM5 and N-type calcium channel, and may enhance channel activities and potentiates fast synaptic transmission by phosphorylating the pore-forming alpha subunit CACNA1B (CaV2.2). In prostate cancer cells, interacts with and phosphorylates STAT3, which increases DNA-binding and transcriptional activity of STAT3 and seems to be essential for prostate cancer cell invasion. Downstream of TLR4, plays an important role in the lipopolysaccharide (LPS)-induced immune response by phosphorylating and activating TICAM2/TRAM, which in turn activates the transcription factor IRF3 and subsequent cytokines production. In differentiating erythroid progenitors, is regulated by EPO and controls the protection against the TNFSF10/TRAIL-mediated apoptosis, via BCL2. May be involved in the regulation of the insulin-induced phosphorylation and activation of AKT1. Phosphorylates NLRP5/MATER and may thereby modulate AKT pathway activation in cumulus cells. Phosphorylates and activates LRRK1, which phosphorylates RAB proteins involved in intracellular trafficking.
Synonyms: PKCE; nPKC-epsilon
Tractability: Small molecule: an approved drug acts on it; a structure with a bound ligand is known; a high-quality ligand is known; it belongs to a druggable protein family. Antibody: UniProt places it where antibodies can reach, with high confidence; its Gene Ontology location is reachable by antibodies, with high confidence; the Human Protein Atlas places it where antibodies can reach. PROTAC: ubiquitination databases record sites on it; its protein half-life has been measured; a small molecule that binds it is known. Other modalities: a drug acting on it is in phase 2 or 3 trials.
Target class: Kinase; AGC protein kinase PKC family; Protein Kinase; AGC protein kinase group; Enzyme; AGC protein kinase PKC eta subfamily
Chemical probes: CHELERYTHRINE
Safety:
Unwanted effects reported when the protein is acted on. In parentheses: how it was acted on, where the effect was seen, and who reports it.
cardiac arrhythmia (cardiovascular system; source: Lamore et al. (2017))
Esophagitis (source: ClinPGx)
hypertension (source: ClinPGx)
Gene: Protein-coding gene on chromosome 2 (45,651,205 to 46,187,990, forward strand). Ensembl gene ENSG00000171132.
Subcellular location: Cytoplasm; Cytoplasm, cytoskeleton; Cell membrane; Cytoplasm, perinuclear region; Nucleus
Subcellular location (Human Protein Atlas): Cytosol; Intermediate filaments; Plasma membrane; Vesicles
Pathways (Reactome):
Signal Transduction: DAG and IP3 signaling; G alpha (z) signalling events; SHC1 events in ERBB2 signaling
Hemostasis: Effects of PIP2 hydrolysis
Immune System: Role of phospholipids in phagocytosis
Gene Ontology:
Molecular function: calcium,diacylglycerol-dependent serine/threonine kinase activity; diacylglycerol-dependent, calcium-independent serine/threonine kinase activity; enzyme activator activity; enzyme binding; protein binding; protein kinase activity; protein serine kinase activity; protein serine/threonine kinase activity; actin monomer binding; diacylglycerol-dependent serine/threonine kinase activity; 14-3-3 protein binding; ATP binding; ethanol binding; signaling receptor activator activity
Biological process: positive regulation of cytokinesis; positive regulation of epithelial cell migration; positive regulation of wound healing; regulation of actin cytoskeleton organization; toxin catabolic process; xenobiotic catabolic process; apoptotic process; Fc-gamma receptor signaling pathway involved in phagocytosis; intracellular signal transduction; lipopolysaccharide-mediated signaling pathway; negative regulation of sodium ion transmembrane transport; positive regulation of actin filament polymerization; positive regulation of fibroblast migration; positive regulation of protein localization to plasma membrane; positive regulation of superoxide anion generation; signal transduction; TRAM-dependent toll-like receptor 4 signaling pathway; negative regulation of protein ubiquitination; regulation of metal ion transport; regulation of monoatomic cation transmembrane transport
Cellular component: cytoplasm; cytosol; endoplasmic reticulum; intermediate filament cytoskeleton; plasma membrane; cell periphery; Golgi apparatus; nucleus; perinuclear region of cytoplasm; cytoskeleton; membrane; mitochondrion
Genetic constraint (gnomAD): Loss-of-function variants: 16 observed, 87.41 expected, observed/expected ratio (o/e) 0.18, 90% interval 0.12 to 0.28. The upper end of that interval is the gene's LOEUF score, 0.28, which puts it in group 1 of 6, group 1 being the genes least tolerant of losing a copy. Missense variants: 573 observed, 999.91 expected, observed/expected ratio (o/e) 0.57, 90% interval 0.53 to 0.61. Synonymous variants: 388 observed, 386.91 expected, observed/expected ratio (o/e) 1, 90% interval 0.92 to 1.09.
Homologues: Orthologues: chimpanzee PRKCE (100% identical), macaque PRKCE (99% identical), pig PRKCE (99% identical), dog PRKCE (99% identical), guinea pig PRKCE (99% identical), rat Prkce (99% identical), mouse Prkce (98% identical), rabbit PRKCE (94% identical), tropical clawed frog prkce (92% identical), zebrafish prkceb (86% identical), zebrafish prkcea (86% identical), Caenorhabditis elegans tpa-1 (41% identical), and 6 more. Paralogues in human: PRKCH (60% identical), PRKCA (34% identical), PRKCB (34% identical), PRKCZ (33% identical), PKN2 (32% identical), PRKCG (32% identical), PRKCI (32% identical), PKN1 (31% identical), PKN3 (29% identical).
Diseases named in the same sentence as PRKCE in open-access papers:
PRKCE is named in the same sentence as 72 diseases in open-access papers, as found by Europe PMC text mining. Sharing a sentence is not in itself a finding about the gene and the disease. The quoted sentences say what the papers report.
Insulin resistance (12 papers, 2017 to 2025). Increased resistance towards insulin, that is, diminished effectiveness of insulin in reducing blood glucose levels. "Hepatic insulin resistance is closely associated with increased sn‐1,2 diacylglycerol content, translocation of protein kinase C epsilon (PKCε) to the plasma membrane and subsequent inhibition of insulin receptor kinase activity." (PMID 35088525, 2022). "In many studies involving cultured cells, mouse models and humans, the PRKCE was found being associated with the generation of lipid‐induced insulin resistance in peripheral tissues, and PRKCE was one of the most often implicated isoforms in PKC family (Schmitz‐Peiffer & Biden, 2008)." (PMID 36540634, 2022). "Early study found that overexpression of PRKCE could be associated with the development of insulin resistance by decreasing the insulin receptors in animals." (PMID 35140684, 2021). "Additionally, hepatic insulin resistance, which is caused by diacylglycerol-mediated activation of protein kinase C epsilon (PKCε), may be the critical pathological link between NAFLD and T2DM." (PMID 30692925, 2018). "Among the 10 most upregulated genes in NAFLD were genes related to insulin resistance (PRKCE), glucose metabolism and steatosis (PLIN1), glucose uptake regulation (ISM1), oxidative cell stress response (TP53INP1), and a proinflammatory marker (SERPINE 1)." (PMID 40489530, 2025). "Protein kinase c epsilon (PRKCE) is a protein coding gene with importance for hepatic insulin resistance, as recently investigated was upregulated in NAFLD and cirrhosis." (PMID 40489530, 2025). "The current literature indicated that increased PRKCE activation was related to marked increases TG in liver, which further led to insulin resistance." (PMID 35140684, 2021). "We considered that the PRKCE regulated the lipid abundance, steatosis, insulin resistance, thereby modulated the pathogenetic process of NAFLD." (PMID 34419146, 2021). "PRKCE is already known to play a critical role in mediating fat-induced hepatic insulin resistance through the buildup of diacylglycerol in NAFLD." (PMID 31635436, 2019). "Severe hepatic insulin resistance was characterized using the hyperinsulinemic-euglycemic clamp technique and was attributed to increased hepatic diacylglycerol content and protein kinase C-epsilon activation and decreased insulin activation of Akt2." (PMID 28163820, 2017). "Activation of PRKCE links the NAFLD to hepatic insulin resistance." (PMID 34419146, 2021). "Meanwhile, PRKCE could also impairs insulin signaling and its ability to activate glycogen synthesis and inhibit neoglucogenesis, resulting in insulin resistance." (PMID 35140684, 2021). "Hepatic steatosis leads to hepatic insulin resistance by activating PRKCE." (PMID 34419146, 2021). "Another study that utilized an antisense oligonucleotide against Dgat2 also showed that knocking down Dgat2 protected against fat-induced hepatic insulin resistance due to decreased DAG amount and protein kinase C epsilon activation." (PMID 37644753, 2023).
breast carcinoma (7 papers, 2015 to 2024). "Collectively, this study provides experimental evidence for PRKCE/AURKB/RAB27B axis in regulating the resistance to paclitaxel (PTX) in breast cancer cells, offering a potential intervention target for reversing drug resistance." (PMID 35088239, 2022). "In our experiment, the expression of PRKCE in PTX-resistant breast cancer cells was significantly higher than that in wild-type cells." (PMID 35088239, 2022). "The focus of this study was to explore the influence of Krüppel-like factor 3 (KLF3), tumor protein D52 (TPD52), microRNA 124 (miR-124), and protein kinase C epsilon (PKCε) expression on breast cancer." (PMID 33490232, 2020). "Alternatively, in human breast cancer cells, miR-31 was shown to sensitize these cells to apoptosis by directly targeting protein kinase C epsilon." (PMID 25706292, 2015). "For example, tamoxifen, an FDA-approved inhibitor of the protein kinase C genes PRKCB and PRKCE, currently used for breast cancer treatment, could potentially be used to target EGFR or KRAS-mutated lung cancers and NRAS-mutated skin cancer." (PMID 37863651, 2024). "Collectively, the findings obtained in our study may provide experimental evidence for the involvement of the PRKCE/AURKB/RAB27B axis in the resistance of breast cancer cells to PTX and offer a potential intervention target for reversing tumor drug resistance." (PMID 35088239, 2022). "Only PRKCE (protein kinase C epsilon) has not been linked to estrogen action in breast cancer yet, although this protein has been shown to enhance the survival, anchorage-independent growth, and lung metastasis of the LM3 murine mammary tumor cell line (which lacks PR and ER expression)." (PMID 31614463, 2019). "In our study, related experiments were performed to compare the relative expression of PRKCE mRNA and protein in MDA-MB-231 breast cancer cells and the corresponding PTX-resistant MDA-MB-231/PTX cells." (PMID 35088239, 2022). "Higher expression of PRKCE is reported in multiple cancer types such as HNSCC, breast cancer and lung cancer." (PMID 33931671, 2021). "E2­activated HSF1 was transcriptionally potent and several genes essential for breast cancer cells growth and/or ERα action, including HSPB8, LHX4, PRKCE, WWC1, and GREB1, were activated by E2 in a HSF1-dependent manner." (PMID 31614463, 2019).
gallbladder cancer (5 papers, 2017 to 2025). "Protein kinase C (PRKCE) has been found to be involved in metastasis and malignant transformation and is upregulated in several cancers, such as lung, breast, and gall bladder cancers." (PMID 35620733, 2022). "A particularly significant target is protein kinase C epsilon (PRKCE), a member of the protein kinase C (PKC) family, which has been strongly correlated with unfavorable clinical outcomes in gallbladder carcinoma (GBC)." (PMID 41001034, 2025).
steatosis (5 papers, 2019 to 2025). Increased lipid within the cytoplasm of cells. "Besides, PRKCE is a critical gene in steatosis for NAFLD patients, and NAFLD is a risk factor for T2DM." (PMID 35140684, 2021). "Precious analysis revealed that ANXA2, PRKCE, and OXT are three important genes that are involved in steatosis stage of NAFLD." (PMID 31191837, 2019). "RUNX1 target genes, CCL2 and PIK3CA significantly correlated to NAS, steatosis, inflammation grade and fibrosis score, NOS3 to NAS and inflammation grade and PRKCE to NAS and steatosis grade." (PMID 31635436, 2019). "Deregulation of ANXA2, PRKCE, and OXT is a critical event in steatosis." (PMID 31191837, 2019).
glioblastoma (4 papers, 2016 to 2024). The most malignant astrocytic tumor (WHO grade IV). "Aberrant expression of PRKCB is also linked to glioblastoma, breast and prostate cancer as well as PRKCE overexpression." (PMID 27144431, 2016). "Moreover, in our studies, we discovered that the silencing of PRKCE gene and specifically decline of the expression of PKCɛ caused a significant diminution in the Akt phosphorylation of Ser in position 473 and expression of Akt protein level in both glioblastoma cells." (PMID 29439667, 2018). "To evaluate the correlation between high expression of PKCε and autophagy pathways in glioblastomas, we investigated the influence of PRKCE silencing on global expression of genes engaged in the autophagy process." (PMID 29439667, 2018). "Finally, we identified several lncRNA-TF-gene triplets (including HOTAIR-MXI1-CD58/PRKCE and HOTAIR-ATF5-NCAM1) that are associated with glioblastoma prognosis." (PMID 26943771, 2016).
Hepatic steatosis (4 papers, 2011 to 2024). Steatosis is a term used to denote lipid accumulation within hepatocytes. "The endpoint of this process will be the development of hepatic steatosis, increasing hepatic DAG (diacylglycerol) and hepatic PKCε (protein kinase C-epsilon) activation." (PMID 33316927, 2020).
lung carcinoma (4 papers, 1992 to 2024). "However, many “hits” in this study with no readily apparent representation in the lung cancer methylome-related literature were found, [e.g., PR: DARS, CLDN18, APIP; GB: ARHGEF12 PRKCE], and are likely worthy of pursuit." (PMID 26683690, 2015).
asthma (3 papers, 2015 to 2021). "A metabolomic study of asthmatics indicated that PRKCE might be involved in the sphingolipid metabolism in asthma." (PMID 31924195, 2020). "Evidence from both methods implicated sphingolipid metabolism; in particular, the BN subnetwork of GNA12, PRKCE and S1P, may represent a potential mechanism for asthma control." (PMID 26421150, 2015).
myocardial ischemia (3 papers, 2021 to 2025). A disorder of cardiac function caused by insufficient blood flow to the muscle tissue of the heart. "In our study, the expression level of heart PRKCA was enhanced, while PRKCE was reduced upon myocardial ischemia, and their levels returned to normal following the pretreatment of XML injection." (PMID 35141226, 2022). "Based on the results of network pharmacology analysis, first, the top four genes (PRKCA/MAPK3/PRKCG/PLA2G4A) and PRKCE (an isoform of the large PKC family) were picked up for validation in the animal model of surgery-induced myocardial ischemia." (PMID 35141226, 2022). "In a preclinical study using an animal model of myocardial ischemia/reperfusion (I/R) injury, semaglutide increased GLP-1R expression, activating the PKG/PKCε/ERK1/2 (protein kinase G/protein kinase C epsilon/extracellular signal-regulated kinase 1/2 pathway, which inhibited cardiomyocyte apoptosis." (PMID 40725024, 2025).
prostate carcinoma (3 papers, 2014 to 2021). A carcinoma that arises from epithelial cells of the prostate gland. "Numerous protein kinases including AKT1, MAPK1/ERK, RPS6KA1/RSK1, cAMP-activated protein kinase (PKA), PAK1, PRKCI/nPKC-iota, PRKCE/nPKC-epsilon and PIM1 were reported to phosphorylate BAD in prostate cancer cells." (PMID 33668112, 2021).
renal cell carcinoma (3 papers, 2020 to 2025). "The down-regulation of PRKCE has been indicated to suppresses the proliferation potential, resistance to chemotherapeutics, and tumor formation ability in renal cell carcinoma in vivo." (PMID 32869841, 2020). "Moreover, according to existing research, downregulation of the PRKCE gene can decrease the proliferation potential and tumor formation ability of renal cell carcinoma in vivo." (PMID 35088239, 2022). "Molecular docking findings indicate that the environmental endocrine-disrupting chemical BPA specifically interacts with key targets essential for the function of renal cell carcinoma cells, including CHRM3, GABBR1, CCR4, KCNN4, PRKCE, CYP2C9, HPGD, and FASN." (PMID 41301871, 2025).